CCRL2 (C-C motif chemokine receptor like 2)
Description:
Receptor for CCL19 and chemerin/RARRES2. Does not appear to be a signaling receptor, but may have a role in modulating chemokine-triggered immune responses by capturing and internalizing CCL19 or by presenting RARRES2 ligand to CMKLR1, a functional signaling receptors. Plays a critical role for the development of Th2 responses.
Synonyms: CKRX; CRAM; HCR; CRAM-B; CRAM-A; ACKR5
Tractability: Small molecule: it belongs to a druggable protein family. Antibody: UniProt places it where antibodies can reach, with high confidence; its Gene Ontology location is reachable by antibodies, with high confidence; UniProt predicts a signal peptide or a membrane-spanning region. PROTAC: a small molecule that binds it is known.
Target class: Chemokine receptor-like; Peptide receptor (family A GPCR); Membrane receptor; Family A G protein-coupled receptor
Gene: Protein-coding gene on chromosome 3 (46,407,144 to 46,412,997, forward strand). Ensembl gene ENSG00000121797.
Subcellular location: Cell membrane
Subcellular location (Human Protein Atlas): Plasma membrane; Primary cilium; Primary cilium tip
Pathways (Reactome):
Signal Transduction: Chemokine receptors bind chemokines
Gene Ontology:
Molecular function: CCR chemokine receptor binding; chemokine receptor binding; protein binding; C-C chemokine binding; C-C chemokine receptor activity; chemokine receptor activity; G protein-coupled receptor activity
Biological process: calcium-mediated signaling; cell chemotaxis; chemotaxis; G protein-coupled receptor signaling pathway; immune response; inflammatory response; positive regulation of cytosolic calcium ion concentration; regulation of chemokine activity; chemokine-mediated signaling pathway
Cellular component: plasma membrane; cytoplasm; decoy receptor complex; external side of plasma membrane; membrane
Genetic constraint (gnomAD): Loss-of-function variants: 1 observed, 0.27 expected, observed/expected ratio (o/e) 3.64. That is too few expected variants to judge how well the gene tolerates losing a copy. Missense variants: 451 observed, 429.79 expected, observed/expected ratio (o/e) 1.05, 90% interval 0.97 to 1.13. Synonymous variants: 181 observed, 175.46 expected, observed/expected ratio (o/e) 1.03, 90% interval 0.91 to 1.17.
Homologues: Orthologues: chimpanzee CCRL2 (98% identical), macaque CCRL2 (92% identical), pig CCRL2 (67% identical), dog CCRL2 (62% identical), rat Ccrl2 (52% identical), mouse Ccrl2 (52% identical), tropical clawed frog ccr2 (34% identical), zebrafish cabz01093075.1 (31% identical), zebrafish ccr8.1 (30% identical), zebrafish si:cabz01093077.1 (29% identical), zebrafish si:ch211-207g17.3 (29% identical), zebrafish ccr2 (27% identical), and 1 more. Paralogues in human: CCR1 (41% identical), CCR3 (39% identical), CCR5 (38% identical), CCR2 (37% identical), CCR4 (34% identical), ACKR2 (30% identical), CCR8 (29% identical), CX3CR1 (28% identical), XCR1 (26% identical), ACKR4 (26% identical), CXCR6 (25% identical), CCR7 (25% identical), and 11 more.
Diseases named in the same sentence as CCRL2 in open-access papers:
CCRL2 is named in the same sentence as 76 diseases in open-access papers, as found by Europe PMC text mining. Sharing a sentence is not in itself a finding about the gene and the disease. The quoted sentences say what the papers report.
breast carcinoma (9 papers, 2016 to 2025). "Expression of chemerin receptor genes CMKLR1, GPR1 or CCRL2 is associated with longer survival in ovarian cancer, breast cancer and non-small-cell lung cancer (NSCLC)." (PMID 36077645, 2022). "In breast cancer models, overexpression of CCRL2 has been shown to inhibit CCL2-induced p38 MAPK phosphorylation, resulting in restored E-cadherin expression and reduced cellular invasiveness." (PMID 40867595, 2025). "CCRL2 expressing adipose tissue progenitor cells cooperate to induce epithelial-to-mesenchymal transition (EMT) gene expression in luminal breast cancer cells to enhance tumor progression and metastatic dissemination." (PMID 35754051, 2022). "In breast cancer cells, the constitutive expression of CCRL2 was upregulated in the presence of pro-inflammatory cytokines, such as IL-1β, TNF-α, IL-6, and especially IFN-γ." (PMID 32456359, 2020). "In a recent study demonstrating CCRL2 expression in breast cancer by means of IHC, increased amounts of CCRL2 were found in breast tumor tissues with high immune cell infiltration." (PMID 31370263, 2019). "CCRL2 expression has been reported across a range of malignancies and tumor-derived cell lines, including human glioblastoma, colorectal carcinoma, breast cancer, prostate cancer, and non-small-cell lung cancer." (PMID 40867595, 2025). "Interestingly, by blocking the activity of CCL2 chemokine, CCRL2 suppressed the migration of breast cancer malignant cells and their invasion." (PMID 32456359, 2020). "In human breast cancer cells (MDA-MB-231), overexpression of CCRL2 significantly inhibited colony formation." (PMID 40867595, 2025). "By contrast, CCRL2 overexpression was reported to inhibit CCL2-induced phosphorylation of p38 MAPK leading to decreased chemotaxis and invasion of human breast cancer cells." (PMID 27907906, 2016). "Moreover, CCRL2 retarded invasion and chemotaxis through inhibition of p38 MAPK phosphorylation in breast cancer cells." (PMID 37274231, 2023). "Highly invasive human breast cancer cell lines (MDA-MB-231 and BT-549) were shown to express low levels of CCRL2, and overexpression of the receptor negatively affected the growth of these cells in vitro and in vivo, as well as their chemotactic response to CCL2 and invasive properties." (PMID 34638484, 2021). "Tissue expression of CCRL2 chemerin receptor, which was similar in normal and malignant breast tissue, neither affected RFS nor OS of women with breast cancer." (PMID 31370263, 2019).
glioblastoma (8 papers, 2014 to 2025). The most malignant astrocytic tumor (WHO grade IV). "CCRL2 expression by tumor cells was also described in several human cancer types, including glioblastoma, breast, and colorectal cancer." (PMID 34638484, 2021). "Previous reports have demonstrated that the chemerin receptor CCRL2 upregulation contributes to glioblastoma cell migration, cutaneous squamous cell carcinoma, and acute myeloid leukemia." (PMID 29190935, 2017). "Recent studies have reported the expression of CCRL2 in human cancer cell lines and tissues from breast, colon, glioblastoma, and salivary adenoid cystic carcinoma." (PMID 29497024, 2017). "Expression of CCRL2 has been previously reported in cell lines and tissues from breast, glioblastoma, salivary, and colorectal origin." (PMID 29497024, 2017). "Moreover, the overexpression of CCRL2 significantly enhanced the migration rate and invasiveness of the glioblastoma cells, suggesting for a potential role of CCRL2 as a therapeutic target in these patients." (PMID 24971349, 2014). "Interestingly, CCRL2 overexpression enhanced invasion and migration of glioblastoma cells." (PMID 37274231, 2023). "The elevated CCRL2 expression in other tumors including malignant breast cancer, high grade glioblastoma and cervical carcinoma has been previously postulated to be associated with cell migration, invasion and poor prognosis, irrespective of whether its biological ligands were present or not." (PMID 27907906, 2016). "CCRL2 has been earlier suggested to contribute to glioblastoma (GBM) cell migration and invasion as well as to colorectal liver metastasis." (PMID 27907906, 2016). "CCRL2 overexpression did not modify the proliferation of the human glioblastoma cell lines U87MG and U373MG in vitro but increased the migration and invasive properties of the cells." (PMID 34638484, 2021). "Furthermore, in all types tested, i.e., oligodendroglioma WHO grade II, anaplastic oligoastrocytoma WHO grade III, and glioblastoma WHO grade IV, expression level of CCRL2 correlated significantly in a similar way with the expression of its potential ligands, CCL2 and CCL5." (PMID 32456359, 2020). "Moreover, although CCRL2 did not regulate the growth of human glioblastoma cell lines, its increased expression alone was sufficient to enhance the migration and invasion of glioma tumor cells." (PMID 32456359, 2020).
colorectal cancer (7 papers, 2017 to 2025). A primary or metastatic malignant neoplasm that affects the colon or rectum. "However, CCRL2 is known to increase local chemerin concentrations and its expression has been linked to rheumatoid arthritis and liver metastasis in colorectal cancer." (PMID 29221117, 2017). "Modulation of CCRL2 regulated proliferation, colony formation and migration of colorectal cancer cells." (PMID 37274231, 2023). "Akram, I.G.; Georges, R.; Hielscher, T.; Adwan, H.; Berger, M.R. The chemokines CCR1 and CCRL2 have a role in colorectal cancer liver metastasis." (PMID 31146450, 2019). "Reference 40 to “Akram, I.G.; Georges, R.; Hielscher, T.; Adwan, H.; Berger, M.R. The chemokines CCR1 and CCRL2 have a role in colorectal cancer liver metastasis." (PMID 31146450, 2019). "When rat CC531 colorectal cancer cells were injected into the rat portal vein for liver colonization assays, the initial low CCRL2 mRNA levels increased during initial colonization of the liver." (PMID 31561459, 2019). "The chemokines C-C chemokine receptor type 1 (CCR1) and C-C motif receptor-like 2 (CCRL2) are associated with colorectal cancer liver metastasis: The expression modulation of CCR1 and chemokine CCRL2 were investigated in the same rat liver metastasis model." (PMID 28770169, 2017). "Moreover, the knockdown of CCRL2 affected the clonogenic capacity of different human colorectal cancer cell lines (SW620, Caco2, and LS174T), with a reduction in colony formation for LS174T cells and a slight increase for SW620 and Caco2 cells." (PMID 40867595, 2025). "High levels of CCRL2 and CCR1 were also found in liver metastases of colorectal carcinoma in rats, but the consequences of CCRL2 expression appeared limited in human primary colorectal carcinoma cells in terms of proliferation, clonogenic capacity, migration, and survival." (PMID 34638484, 2021). "Expression of the non-signaling chemerin receptor, CCRL2, was reported to be reduced by about 2/3 in colorectal cancer patients versus disease-free controls." (PMID 31561459, 2019).
prostate carcinoma (6 papers, 2017 to 2025). A carcinoma that arises from epithelial cells of the prostate gland. "High expression of CCRL2 was also described in prostate tumors and the PC-3 prostate cancer cell lines." (PMID 34638484, 2021). "Here, we report for the first time an elevated expression of chemokine receptor CCRL2 in prostate cancer cell lines and tissue samples." (PMID 29497024, 2017). "The key findings of this study constitute a starting point for subsequent research on the biological role and clinical implications of CCRL2 expression in prostate cancer." (PMID 29497024, 2017). "Here, we report that CCRL2 expression level is elevated at the mRNA and protein level in prostate cancer cell lines and prostate cancer tissues." (PMID 29497024, 2017). "It has been reported that overexpression of CCRL2 was found in prostate cancer cells." (PMID 37274231, 2023). "In addition, CCRL2 is overexpressed in a metastatic prostate cancer cells and prostate cancer tissues from patients, both at the mRNA and protein level." (PMID 32456359, 2020). "In addition, immunohistochemistry of prostate cancer tissue specimens in TMA revealed that CCRL2 expression was significantly stronger in epithelial cells of cancerous acini than in those of matched adjacent benign acini from the same patient." (PMID 29497024, 2017). "The biological role of CCRL2 in prostate cancer warrants further investigations." (PMID 29497024, 2017). "CCRL2 protein expression was evaluated by IHC in a TMA arrayed with 231cores from benign prostate tissue and prostate cancer tissue obtained from 47 patients." (PMID 29497024, 2017). "As mRNA for CCRL2 exhibited the most differential expression, it was chosen for further analysis at the protein level in the prostate cancer cell line PC-3 and the non-tumorigenic PWR1-E cells." (PMID 29497024, 2017). "Currently, data on the expression of CCRL2 and its involvement in prostate cancer is lacking." (PMID 29497024, 2017).
COVID-19 (5 papers, 2021 to 2025). A disease caused by infection with severe acute respiratory syndrome coronavirus 2. "Our analysis identified multiple neutrophils-restricted genetic variants targeting CCRL2, which were confirmed in our Italian cohort of COVID-19 hospitalized patients." (PMID 39811276, 2025). "Overall, we propose CCRL2 as a novel susceptibility factor for COVID-19 severity and hospitalization." (PMID 39811276, 2025). "Here, we reported the link between the identified severe COVID-19-linked CCRL2 variants and the total circulating counts of monocytes, granulocytes, and basophils." (PMID 39811276, 2025). "To conclude, the identified CCRL2 eQTLs linked to severe COVID-19 are mostly mapped within active chromatin regions of the 3p21.31 locus that are differentially accessible in neutrophils." (PMID 39811276, 2025). "To conclude, the identified CCRL2 eQTLs linked to severe COVID-19 are mostly mapped within neutrophils' active chromatin regions of 3p21.31, which are targeted by neutrophil-expressed transcription factors." (PMID 39811276, 2025). "Within this boundary, we observe two CCRL2 eQTLs, i.e. rs3181077 (associated with COVID-19 severity in Europeans) and rs1491961, both located in a peak for H3K27Ac histone modifications." (PMID 39811276, 2025). "This association was corroborated by the identification of two haplotypes that link CCRL2 expression levels to severe form of COVID-19 in an Italian cohort of hospitalized severe COVID-19 patients." (PMID 39811276, 2025). "Among the CCRL2 eQTLs identified, three of them were independent significant SNPs in the COVID-19 HGI cohort, thus suggesting a direct association of CCRL2 to COVID-19 severity in European ancestry individuals." (PMID 39811276, 2025). "Haplotype analysis revealed a link between an increased CCRL2 expression and COVID-19 severity and hospitalization." (PMID 39811276, 2025). "Of these genes, 7 are chemokine receptor genes (CCR1, CCR2, CCR3, CCR5, CCR9, CCRL2, and CXCR6), which are likely linked to the segment’s association with COVID-19 severity." (PMID 36763080, 2023). "Notably, in contrast to earlier releases of the COVID-19 HGI dataset, we identified significantly associated SNPs also in proximity of the most distant gene of the CKRs cluster, i.e. CCRL2 (for a total of 45 SNPs in the gene body; Suppl." (PMID 39811276, 2025). "In fact, CCRL2 and CXCR2 expression levels were upregulated in circulating neutrophils from COVID-19 patients." (PMID 39811276, 2025). "Seven of our significant genes higher (GALNT14, OAS1, CCRL2, OAS3, CCR1, OAS2, SIPA1L2) in COVID-19 and two lower (HLA-DPB1, HLA-DQA2) were identified to overlap." (PMID 34335605, 2021). "CCRL2, LZTFL1, SCAP, and SACM1L are also differentially expressed in at least one experiment that measures differential expression of genes in lung tissues and related cell lines infected with COVID-19 or other viruses that stimulate similar immune responses." (PMID 36763080, 2023). "Therefore, an overall increase in neutrophils CCRL2 expression could significantly impair the proper CXCR2-mediated neutrophil trafficking in COVID-19 patients, thus resulting in a neutrophil hyperactivation state and subsequent severe COVID-19." (PMID 39811276, 2025).
Arthritis (4 papers, 2017 to 2025). Inflammation of a joint. "Similarly, neutrophils infiltration to inflamed joints was impaired in Ccrl2-deficient mice tested in collagen induced-and serum transfer induced- arthritis, two experimental models of inflammatory arthritis." (PMID 33363177, 2020). "CCRL2 was shown to regulate inflammatory reactions in diverse pathological conditions, including hypersensitivity reactions, arthritis, and experimental autoimmune encephalitis, but its role in cancer has been investigated in few studies so far." (PMID 34638484, 2021). "Importantly, combined methylation sequencing and mRNA sequencing results show that, compared to the arthritis group, the m6A levels of C-C motif chemokine receptor like 2 (CCRL2) mRNA in the synovium of mice treated with Rh2-pre Exo were significantly elevated." (PMID 40502627, 2025). "In human neutrophils, the expression of CCRL2 was increased by proinflammatory stimuli, such as LPS or TNF-α alone or in combination with IFN-γ or GM-CSF and in neutrophils isolated from inflamed joints of arthritis patients." (PMID 33363177, 2020). "At the time of writing, the same group more recently reported a new study in which mice lacking Ccrl2 were protected in two murine models of arthritis in contrast to their previous study using the EAE model, highlighting the complexity of the chemerin/Ccrl2 axis." (PMID 29209334, 2017).
lung carcinoma (4 papers, 2023 to 2025). "In tumors, CCRL2 is actively involved in the NK-mediated lung immune surveillance in mouse models of lung cancer and has been also reported to be a novel marker for aged TAN (tumor-associated neutrophils) from NSCLC (non-small cell lung cancer) patients." (PMID 39811276, 2025). "CCRL2 is involved in immune processes and lung cancer growth." (PMID 39020437, 2024). "CCRL2 expression as required for immune surveillance and anti-tumor immunotherapy in lung cancer." (PMID 37274231, 2023).